CCND1 (cyclin D1)
Diseases named in the same sentence as CCND1 in open-access papers (continued):
Sharing a sentence is not in itself a finding about the gene and the disease.
breast cancer (continued). "Many studies have indicated a significant association between high cyclin D1 expression and clinical outcome of patients not only in HSC but also several other types of cancers such as lung cancer, pancreatic cancer, breast cancer, melanoma and multiple myeloma." (PMID 25437003, 2014). "Cyclin D1, encoded by Ccdn1 gene which is located on chromosome 11q13, forms the regulatory subunit of cyclin-dependent kinases 4 (CDK4) and, was found to be overexpressed in 50% of breast cancers." (PMID 25364741, 2014). "Notably, this gene is amplified in about 20 % of human breast cancers and the cyclin D1 protein is expressed at increased level in about 50 % of human breast tumors." (PMID 22926504, 2014). "ER beta has been shown to inhibit human breast cancer cell proliferation by repressing transcription of the c-myc, cyclin D1 and cyclin A genes and increasing the expression of the cyclin-dependent kinase inhibitors p21Waf1/Cip1 and p27Kip1, leading to cell cycle arrest in the G2 phase." (PMID 24552459, 2014). "A well-known example of this cross-talk is in the estrogen-dependent regulation of the Ccnd1 gene in breast cancer cells, where membrane-initiated activation of PI3K/AKT and ERK signaling, as well as ERE-dependent mechanisms are necessary for maximal estrogen-stimulated transcription." (PMID 24776842, 2014). "Anti-cyclin D1 antibodies recognizes a 43-kD protein in mammary tumors at various ages." (PMID 25230850, 2014). "As a first step, we performed routine genotype work, but results showed CCND1 A870G genotype not linked with breast cancer susceptibility." (PMID 25520916, 2014). "The miR-17/20-mediated inhibition of breast cancer cellular proliferation via cyclin D1 repression, together with the finding that miR-17/20 inhibits breast cancer cell invasiveness, is consistent with a model in which miR-17/20 is a negative growth regulator in breast cancer cells." (PMID 24658544, 2014). "However, determining the direct contribution of EMSY to breast cancer has been difficult because the gene resides within the 11q13-11q14 locus, containing a cassette of genes, including several known and potential breast cancer drivers (CCND1, PAK1, and RSF1)." (PMID 24582497, 2014). "For example, it can directly regulate the cell cycle and induce proliferation by inducing cyclin D1 in breast cancer, cyclin D1, cyclin E, and c-Myc in colon cancer, or by promoting CDK2 kinase activity while repressing the p27 cell cycle suppressor in prostate cancer cells." (PMID 25309874, 2014). "The E2-induced Vav1 level in breast cancer cells was in favor of promoting Cyclin D1 expression and accelerating the cell proliferation, and Vav1 might partially contribute to the pathogenesis and prognosis of breast cancer." (PMID 24905577, 2014). "Moreover, we observed that expression of cyclin D1, a critical regulator of G1 phase progression of breast cancer cells was found to be significantly downregulated in Smurf2 siRNA treated cells." (PMID 25191523, 2014). "Cyclin D1 is important for the development and progression of breast cancer." (PMID 24915301, 2014). "Cyclin D1 was detected at high levels in approximately 50% of breast cancer patients examined." (PMID 24931005, 2014). "Importantly, AP-1 activity governs the transcriptional induction of cyclin D1 to promote the enhanced proliferation of established breast cancer cells." (PMID 25260534, 2014). "Salinomycin reduces cyclin D1 level in Hs578T breast cancer cells." (PMID 25531367, 2014). "In breast cancer cells, Han and colleagues found that knockdown of Nanog resulted in inhibited cell proliferation, G0/G1 arrest of the cell cycle, and suppressed expression of cyclin D1 and oncogene c-Myc." (PMID 25322154, 2014).
breast cancer (continued). "Abnormal cyclin D1 expression is common in female breast cancer." (PMID 23755153, 2014). "While this protein is overexpressed in over half of breast cancer cases,cyclin D1 levels in MCF-7 cells are similar to those found in normal mammary epithelial cells, yet cyclin D1 has been shown to play an essential role in cell cycle progression in MCF-7 cells." (PMID 24152862, 2013). "In another study of 1,740 breast cancer patients, cyclin D1 expression was not tightly associated with proliferative genes that are regulated by the inactivation of CDK4 substrate RB." (PMID 23786849, 2013). "The knockdown of FLOT1 reportedly suppressed the proliferation and tumorigenesis of breast cancer cells by enhancing the transcriptional activity of FOXO3a, inhibiting Akt activity, downregulating cyclin D1 and upregulating the cyclin-dependent kinase inhibitors p21Cip1 and p27Kip1." (PMID 24330780, 2013). "TIP48 appears to be necessary for recruiting H2A.Z to the CCND1 gene in MCF-7 mammary tumor cells." (PMID 23637611, 2013). "Given that TGFβ enhanced cyclin D1 and p21 expression and complex formation in these human metastatic breast cancer cells, we investigated whether the TGFβ pro-migratory effect is mediated through cyclin D1." (PMID 23786849, 2013). "In addition, high cyclin D1 expression significantly increased breast cancer-specific survival and overall survival in our cohort." (PMID 23336272, 2013). "Furthermore, using gene silencing approaches, our results indicate that TGFβ-mediated cyclin D1 expression is a prerequisite for TGFβ-induced breast cancer cell migration." (PMID 23786849, 2013). "High cyclin D1 expression statistically significantly correlated with lower tumor grade, estrogen and progesterone receptor positivity and lower proliferation activity in breast tumors and increased breast cancer-specific survival and overall survival." (PMID 23336272, 2013). "Therefore, TCDD inhibition of CCND1 expression is likely to be one of the major mechanisms that inhibit mitogenic adipokine signaling in breast cancer cells." (PMID 24171117, 2013). "CCND1 amplification on chromosome 11q13 occurs in about 10% of breast cancer, and the associated cyclin D1 overexpression has been correlated with a lack of response to tamoxifen." (PMID 24367492, 2013). "Moreover, we found that following fat pad transplantation, parental breast cancer cells invaded into the surrounding mammary tissues, while these effects were blocked when cyclin D1 and p21 gene expression were silenced." (PMID 23786849, 2013). "Taken together, these data suggest that targeted inhibition of constitutive CCND1/CDK2 activity may enhance the effectiveness of current treatments for luminal breast cancer." (PMID 23390492, 2013). "Eugenol inhibited also several other breast cancer related oncogenes, such as NF-κB and cyclin D1." (PMID 24330704, 2013). "Furthermore, depletion of cyclin D1 and p21 prevented mammary tumor formation and subsequent local invasion into surrounding tissues." (PMID 23786849, 2013). "In addition, our data confirm earlier findings correlating high cyclin D1 expression with a good prognosis for breast cancer." (PMID 23336272, 2013).
breast cancer (continued). "In addition, we performed immunohistochemistry on primary mammary tumor derived from animals injected with parental and p21/cyclin D1-depleted SCP2 cells." (PMID 23786849, 2013). "SC-1 and SC-43 induced more potent apoptosis than sorafenib, in association with downregulation of p-STAT3 and its downstream proteins cyclin D1 and survivin in a dose-dependent manner in breast cancer cell lines (HCC-1937, MDA-MB-468, MDA-MB-231, MDA-MB-453, SK-BR3, MCF-7)." (PMID 23938089, 2013). "Cyclin D1 is a very important cell cycle regulator and is reported to be oncogenic in breast cancer, and it was also reported to be a faithful target of HIF2α that might play an important role in kidney cancer." (PMID 24260413, 2013). "CG0009 induced complete depletion of cyclin D1 in sensitive breast cancer cells." (PMID 23565238, 2013). "Cyclin D1 was statistically significantly correlated with estrogen and progesterone receptor positivity, a lower tumor grade and lower proliferation activity, that is, with breast cancers that have a good prognosis." (PMID 23336272, 2013). "Analysis of transcript co-regulation in our samples showed that additional genes are expressed in parallel with GATA3, including those coding for carbonic anhydrase XII (CA12), cyclin D1 (CCND1) or hepsin (HPN), all of which have been associated with breast cancer." (PMID 24205108, 2013). "Collectively, these results indicate that while p21 and cyclin D1 are required for breast cancer cells to acquire an invasive phenotype, their effects are primarily occurring at the earlier stages of tumor metastasis, namely induction of local cell invasion from the tumor to the surrounding tissues." (PMID 23786849, 2013). "Our previous study showed that p21 is required for TGFβ-mediated cell migration and invasion; therefore, these results not only highlight cyclin D1 as a novel TGFβ downstream target, but also indicate that cyclin D1 cooperates with p21 to mediate the effect of TGFβ on breast cancer progression." (PMID 23786849, 2013). "To address the importance of p21 and cyclin D1 on breast cancer development in vivo, we injected either SCP2 control or double p21 and cyclin D1 knockdown cells into the mammary fat pads of female Balb/c nude mice to monitor primary tumor growth and local invasiveness." (PMID 23786849, 2013). "To gain a better understanding of the early steps required in estrogen receptor mediated transcription activation and the coordination between remodeling complexes and chromatin structure, we analyzed transcription of the cyclin D1 gene (CCND1) in ERα-positive MCF-7 breast cancer cells." (PMID 23637611, 2013). "Interestingly, we found that GL and z-Gug significantly inhibit the protein expression of Wnt/β-Catenin downstream effectors c-Myc, cyclin D1 and survivin in both breast cancer cells." (PMID 23914993, 2013). "Cyclin D1 expression has been shown in previous human breast cancer studies to correlate with positive ER status, the protein being predominantly expressed in the well-differentiated, low-grade, slow-growing subtypes of breast cancer." (PMID 23336272, 2013). "It is well known that cyclin D1 is the target gene of Hh signaling in breast cancer." (PMID 23861764, 2013). "This suggests that down-regulation of cyclin D1 and CDK4 may be associated with ST-induced G1 phase arrest in breast carcinoma cells." (PMID 24160369, 2013). "Recent study suggested that CCND1 increased the migratory ability and cause EMT in breast cancer." (PMID 23284982, 2012). "Our data support studies indicating that low cyclin D1 protein expression as well as CCND1 amplification are linked to tumour aggressiveness and increased risk of disease recurrence in ER-positive postmenopausal breast cancer." (PMID 22475046, 2012). "In addition, cyclin D1 is a critical downstream target of ErbB2-, Ras- and β-catenin- induced breast cancers, and is sufficient for the induction of mammary tumors when targeted to the mammary gland of mice." (PMID 22382486, 2012).
breast cancer (continued). "Estrogen receptor alpha (ERα) and cyclin D1 are frequently co-expressed in human breast cancer." (PMID 24575359, 2012). "We previously reported that STAT5b may mediate the transcriptional activation of IGF-1 and cyclin D1 after hypoxic stimulation in human breast cancer cells." (PMID 22485142, 2012). "Overexpression of cyclin D1 protein has been linked with both positive (most likely due to associations with ER + tumors) and negative breast cancer prognosis." (PMID 22924091, 2012). "Worryingly, amplification of CCND1 was further linked to a potentially detrimental effect of tamoxifen in premenopausal breast cancer patients, when compared with randomised control patients not receiving any adjuvant therapy." (PMID 22475046, 2012). "In addition to estrogen signaling and resistance to therapy, 7 of the identified genes have been previously associated with cell cycle regulation (CCND1, CDKN1A, CDKN1B, and CDKN2A) and breast cancer aggressiveness (CLDN7 and DLC1)." (PMID 22616718, 2012). "The CCND1 amplification status and protein expression of cyclin D1 were assessed by chromogenic in situ hybridisation and immunohistochemistry, respectively, in 1,155 postmenopausal, oestrogen-receptor-positive breast cancer patients included in the TransATAC substudy." (PMID 22475046, 2012). "This study confirms that the cyclin D1 status provides independent prognostic information regarding ER-positive, postmenopausal breast cancers, supporting its emerging role as a biomarker that might be useful in the clinic." (PMID 22475046, 2012). "DBC2 suppresses breast cancer cells proliferation through down-regulation of cyclin D1 (CCND1)." (PMID 23626933, 2012). "Cyclin D1 is amplified and or overexpressed in a subset of human cancers including breast cancer." (PMID 23351343, 2012). "When focusing on the non-amplified breast cancer samples, high cytoplasmic cyclin D1 protein expression was indeed associated with a better outcome (P = 0.005)." (PMID 22475046, 2012). "Our data suggest that eEF-2K may enhance tumorigenesis through the up-regulation of pro-tumorigenic proteins and pathways including cyclin D1, c-Myc, c-Src/FAK and Akt whose dysregulation are associated with a poor prognosis in breast cancer." (PMID 22911754, 2012). "More specifically, a number of compounds related to cell proliferation (aromatase, MAPK, and cyclin D1), apoptosis (Bcl2 and caspase 8), cell-cycle regulation (AMPK), and cell survival (Akt) have been implicated to mediate tumorigenesis in breast cancer cell lines." (PMID 22295251, 2012). "In addition, estrogen signaling increases proliferation of breast cancer cells by upregulating expression of cell cycle enhancers (e.g., cyclin D1) and transcription factors (e.g., c-myc and E2F) expression in breast cancer." (PMID 22291950, 2012). "For instance, such subtypes could differ by the status of HER2, which is known to play an important role in breast cancer carcinogenesis or statuses of other potential breast cancer biomarkers (such as Ki67, Cyclin D1, Estrogen Receptor β)." (PMID 23166647, 2012). "In male breast cancer CCND1 and EGFR were more often gained than in the female breast cancer group." (PMID 22527098, 2012). "We found that in the nucleus of breast cancer cells, ErbB-2 assembles a transcriptional complex in which it functions as a coactivator of the signal transducer and activator of transcription 3 (Stat3) to promote the expression of cyclin D1, another gene known to induce breast cancer proliferation." (PMID 22356700, 2012). "Cyclin D1 is either overexpressed or amplified in ~50% of breast cancer." (PMID 22382486, 2012). "Previous work by our group revealed a novel induction of breast cancer cell migration after cyclin D1 silencing, which may account for a worse clinical outcome for patients with low expression of the protein." (PMID 21955753, 2011).
breast cancer (continued). "In addition, Ezh2 (but not other PcG proteins) was found as a transcriptional activator of c-Myc and cyclin D1 in a breast cancer cell line." (PMID 21624129, 2011). "As a role for Id1 in breast cancer cell metastasis and aggressiveness has previously been suggested, it was logical to examine whether it was also responsible for the cyclin D1 induced increase in cell migration." (PMID 21955753, 2011). "Whilst two studies have reported an association of the variant Pro241Pro in CCND1 with breast cancer risk, other studies have reported negative results for this variant." (PMID 21269472, 2011). "Rather, the effect relies on a direct decrease in cyclin D1, strongly suggesting that inhibition of cyclin D1 by Buxus extract could be a good tool to improve prognosis in breast cancer." (PMID 21935420, 2011). "Since human breast cancers show increased abundance of CCND1, CCND1 might serve as a preferred target in this individual intracellular environment." (PMID 21283765, 2011). "Additionally, C/EBPbeta2 is expressed in breast cancer cell lines and can transactivate cyclin D1 and PLAC1, two genes whose protein products are involved in proliferation and commonly upregulated in breast cancer." (PMID 21980398, 2011). "However, cyclin D1 overexpression was significantly associated with oestrogen receptor status in only the Caucasian (p = 0.0005), and not the AA cases (p = 0.07) which suggested a biological difference, which may contribute to the more aggressive phenotype of African American breast cancer." (PMID 21410943, 2011). "Previous studies have shown an increased abundance of cyclin D1 in Wnt1 mammary tumors." (PMID 20565980, 2010). "Furthermore, our data suggest that BEX2 expression is required for the normal cell cycle progression during G1 in breast cancer cells through the regulation of cyclin D1." (PMID 20482821, 2010). "Transactivation of β-catenin correlated significantly with cyclin D1 expression, and that high β-catenin activity significantly correlated with poor prognosis of the patients and was a strong and independent prognostic factor in breast cancer." (PMID 20074374, 2010). "Moreover, we have previously reported that BEX2 down-regulation in breast cancer cells leads to a G1 arrest and a significant reduction of cyclin D1 expression." (PMID 20482821, 2010). "Since cyclin D1 was reported as the key regulatory protein for progression through the G1 phase of breast cancer cells, we next examined whether the expression of cyclin D1 was responsible for the G0/G1 cell cycle arrest in IKKε siRNA-treated cells." (PMID 20863366, 2010). "Interestingly, Cyclin D1 (which was higher in the HIF2+ tumors) has been shown in an in vivo mouse mammary cancer model to reduce the expression of both HK-II and LDH5." (PMID 20652061, 2010). "Cyclin D1, regulated by the NF-κB pathway, is overexpressed in more than 50% of breast cancers, and is identified as one of the most commonly upregulated proteins in breast cancer." (PMID 20863366, 2010). "Furthermore, published in vitro data suggested that retinoids reduce cyclin D1 expression in human breast cancer cell lines." (PMID 22276018, 2009). "CGK733 also induced ubiquitin-dependent loss of cyclin D1 in LNCaP prostate cancer cells, indicating that this effect is not breast cancer specific." (PMID 19903334, 2009). "Moreover, CDK4-associated kinase activity is required to maintain breast tumorigenesis in this system and a subset (~25%) of HER2-amplified breast cancers also have high cyclin D1 levels." (PMID 19874578, 2009). "The role of cyclin D1 as a marker of breast cancer prognosis is somewhat speculative and contradictory results have been published." (PMID 19615042, 2009). "Jirstrom and coworkers reported that CCND1 amplification was associated with a potential agonistic effect of tamoxifen in ER-α-positive premenopausal breast cancer patients, even when not accompanied by protein over-expression." (PMID 18823530, 2008).